ARSB (arylsulfatase B)
Diseases named in the same sentence as ARSB in open-access papers (continued):
Sharing a sentence is not in itself a finding about the gene and the disease.
cystic fibrosis (2 papers, 2022 to 2025). Autosomal recessive disorder caused by pathogenic variants in the CFTR gene (cystic fibrosis transmembrane conductance regulator), which encodes a chloride and bicarbonate channel expressed in epithelial cells, and follow the diagnosis criteria. "ARSB removes 4-sulfate groups from N-acetylgalactosamine 4-sulfate residues and is required for the degradation of chondroitin 4-sulfate (chondroitin sulfate A) and dermatan sulfate, two sulfated glycosaminoglycans which accumulate in cystic fibrosis." (PMID 40362587, 2025). "In human bronchial epithelial cells, expression of MMP-9 was increased when ARSB was lower, as in uncorrected cystic fibrosis cells, or following ARSB silencing." (PMID 36361933, 2022). "In experiments with the cystic fibrosis cell line IB3-1, the CFTR-corrected C38 bronchial epithelial cell line, and the normal primary human bronchial epithelial cells, when ARSB was silenced, IL-8 secretion declined following exposure to TNF-α." (PMID 36361933, 2022). "The treatment of human cerebrovascular cells, placental cells, and bronchial epithelial cystic fibrosis cells, corrected or uncorrected for CFTR, by chloroquine (50 nM × 24 h), significantly reduced the ARSB activity, protein, and mRNA." (PMID 36361933, 2022).
Multiple sulfatase deficiency (2 papers, 2010 to 2022). "Diagnosis generally requires evidence of clinical phenotype, arylsulfatase B enzyme activity <10% of the lower limit of normal in cultured fibroblasts or isolated leukocytes, and demonstration of a normal activity of a different sulfatase enzyme (to exclude multiple sulfatase deficiency)." (PMID 20385007, 2010).
Parkinson’s (2 papers, 2022 to 2024). "In addition to ARSB, 38 significant genotype-by-environment single-nucleotide polymorphisms (P-value ≤ 5E-05) were also detected, thereby implicating ≥ 36 positional candidate genes; the majority of which have also been associated with aspects of Parkinson’s, Alzheimer’s, and prion diseases." (PMID 35536181, 2022).
Stroke (2 papers, 2017 to 2025). Sudden impairment of blood flow to a part of the brain due to occlusion or rupture of an artery to the brain. "The outcome of this study highlight a potential role for arylsulfatase B in promoting atherosclerosis-related stroke and warrants its further investigation as a therapeutic target that could be of potential clinical benefit." (PMID 28659610, 2017).
adenoma (1 paper, 2022). A neoplasm arising from the epithelium. "ARSB immunostaining in a human colonic microarray showed differences in distribution, intensity, and pattern of ARSB staining among normal colon, adenomas, and adenocarcinomas." (PMID 36361933, 2022).
Anxiety (1 paper, 2024). Intense feelings of nervousness, tension, or panic often arise in response to interpersonal stresses. "•Increasing CS 4-0 by silencing ARSB improved anxiety and prevented cocaine preference." (PMID 38880242, 2024). "Notably, the downregulation of ARSB decreased anxiety in mice and increased their preference for novelty over cocaine during withdrawal, suggesting that restoring the levels of CS 4-0 altered by the treatment with cocaine can reduce the severity of withdrawal manifestations." (PMID 38880242, 2024).
atherosclerosis (1 paper, 2017). A disease characterized by the build-up of fatty material and calcium deposition in the arterial wall resulting in partial or complete occlusion of the arterial lumen. "We validated the differential expression of ARSB which was upregulated 1.15-fold (P = 0.029) in atherosclerosis from symptomatic patients." (PMID 28659610, 2017).
bladder tumours (1 paper, 2017). "An increase in the activities of arylsulfatase B (ASB) has been reported in bladder tumours." (PMID 29117212, 2017).
diabetes (1 paper, 2014). "The results demonstrated that diabetes causes a significant elevation in the level of hepatic arylsulfatase B and a significant reduction of hepatic catalase as an antioxidant enzyme." (PMID 25516848, 2014).
Hepatic Carcinoma (1 paper, 2022). "In human hepatic carcinoma tissue and in the malignant hepatic cell line HepG2, ARSB activity was reduced compared to normal control, and the expression of Glycoprotein Nonmetastatic Melanoma Protein B (GPNMB) was increased in hepatic tissue of ARSB null mice and ARSB silenced hepatic cells." (PMID 36361933, 2022).
hippocampal atrophy (1 paper, 2009). "Elucidating the roles of PRUNE2, MAGI2, ARSB and EFNA5 in the regulation of neurodevelopment, protein degradation, apoptosis and neuronal loss could enhance our understanding of hippocampal atrophy and AD." (PMID 19668339, 2009).
Inguinal hernia (1 paper, 2021). Protrusion of the contents of the abdominal cavity through the inguinal canal. "Despite a clear physical examination, the patient's history of inguinal hernia repair, the detection of ARSB:p.Arg159Cys variant, and positive results of ARSB enzyme activity in DBS, this patient was suspected with MPS VI." (PMID 35186827, 2021).
Insulin resistance (1 paper, 2020). Increased resistance towards insulin, that is, diminished effectiveness of insulin in reducing blood glucose levels. "Previously, galectin-3 was shown to bind less to chondroitin 4-sulfate when ARSB was reduced, and to bind with the insulin receptor and contribute to insulin resistance." (PMID 32377523, 2020). "Hence, increased ARSB activity may lead to a decline in serum galectin-3 and to reduced insulin resistance." (PMID 32377523, 2020).
lung carcinoma (1 paper, 2021). "However, as the authors refer, there are some cases of cancer cells where arylsulfatases (ARS) are overexpressed (ARSA and ARSB), as in human lung cancer, pertaining to one of the cell lines tested that yielded lower toxicity of extracts, comparatively to fibroblasts." (PMID 33445445, 2021).
Lysosomal disease (1 paper, 2023). "Mucopolysaccharidosis VI (MPS VI) is a rare lysosomal disease arising from impaired function of the enzyme arylsulfatase B (ARSB)." (PMID 37751300, 2023).
malaria (1 paper, 2025). Malaria is a serious and sometimes fatal disease caused by a parasite that commonly infects a certain type of mosquito which feeds on humans. "In the remote past, declines in CFTR and ARSB may have provided a selective advantage to humans against malaria, since malarial-infected red blood cells bind less well to the endothelium when chondroitin 4-sulfate is more sulfated, implying a survival benefit against malaria from ARSB deficiency." (PMID 40362587, 2025).
mucolipidosis type II (1 paper, 2025). Mucolipidosis II (MLII) is a slowly progressive lysosomal disorder characterized by growth retardation, skeletal abnormalities, facial dysmorphism, stiff skin, developmental delay and cardiomegaly. "Indeed, triclabendazole reduced the transduced GAG core proteins in the MPS model cells, including IDUA KO cells, ARSB KO cells, and GUSB KO cells, as well as in GNPTAB KO cells, a model cell for mucolipidosis type II." (PMID 40822349, 2025).
psychosis (1 paper, 2020). "An example is ARSB, a top biomarker from discovery, and our strongest predictor for low memory state in subjects with psychosis (SZ, SZA), with an AUC of 0.88/p-value 1.04E-03." (PMID 31792364, 2020).
tumor (11 papers, 2016 to 2026). "In line to these data, we previously proved that a low circulating level of ARSB gene (<0.5) is associated with double ARSB/maspin positivity of tumor cells and high grade of tumor budding, probably as an indicator of EMT." (PMID 33498377, 2021). "Inverse effects of rhARSB and ARSB knockdown on phospho(Ser473)-AKT1 indicate that ARSB acts as a tumor suppressor and that a decline in ARSB is pro-oncogenic." (PMID 40562100, 2025). "Tumors appeared earlier, grew faster and attained larger size in untreated mice, compared to mice which received exogenous ARSB, shown on Days 11, 13, and 14 post tumor inoculation." (PMID 37813168, 2024). "The survival at 21 days post tumor inoculation was greater in the ARSB-treated mice than in the control mice (p = 0.039, log-rank test)." (PMID 38892038, 2024). "The mean tumor volume in the total group of ARSB-treated mice was 0.23 ± 0.15 cm3 (n = 28) and 1.05 ± 0.7 cm3 in the control group (n = 9) on day 16 (p = 0.006, unpaired t-test, two-tailed, unequal variance)." (PMID 38892038, 2024). "In the ARSB-treated tumor tissue, free galectin-3 and nuclear Sp1 declined, compared to the control." (PMID 37813168, 2024). "ARSB is required for the degradation of C4S, identified as an oncofetal, tumor-agnostic antigen." (PMID 42306793, 2026). "Doses of ARSB ranged from 0.1 to 0.4 mg/kg administered SC around the tumor." (PMID 37813168, 2024). "It is possible that a decline in abundance of CSPG4 and CHST15 by treatment with exogenous ARSB may improve recognition of the tumor cells by infiltrating immune cells or may enhance contact inhibition." (PMID 37813168, 2024). "Since previous cell-based experiments indicated that silencing of ARSB and the associated increase in chondroitin 4-sulfation enhanced the binding of SHP-2 (PTPN11) with C4S and reduced the SHP2 activity, the impact of exogenous ARSB on SHP2 in the tumor tissue was addressed." (PMID 37813168, 2024). "The newly directed attention to the impact of ARSB in human pathobiology indicates a broader, more pervasive effect, encompassing roles as a tumor suppressor, transcriptional mediator, redox switch, and regulator of intracellular and extracellular-cell signaling." (PMID 36361933, 2022). "Moreover, due to the existing link between Wnt signaling pathway, ARSB, maspin and angiogenesis, a simultaneous inhibition of angiogenesis, tumor cell metabolism and EMT might be obtained through maspin modulation targeted therapy." (PMID 33498377, 2021). "Hence, ARSB may act as a tumor suppressor and GALNS as a proto-oncogene due to their impact on chondroitin sulfation and inhibition of SHP2." (PMID 32595831, 2020). "In vivo experiments showed that local treatment with exogenous N-acetylgalactosamine-4-sulfatase (Arylsulfatase B; ARSB) led to reduced tumor growth over time (p < 0.0001) and improved the probability of survival up to 21 days (p = 0.0391)." (PMID 37813168, 2024). "In the tumor tissues, mRNA expression of CSPG4 and CHST15 declined following treatment with exogenous ARSB (p < 0.001, two-sample t-test, two-tailed, unequal variance, n = 6)." (PMID 37813168, 2024). "SHP2 has been identified as a tumor suppressor in hepatocellular malignancies, and the inhibition of SHP2 when ARSB is reduced is consistent with the role of ARSB as a tumor suppressor." (PMID 27078017, 2016).
cancer (6 papers, 2016 to 2023). A tumor composed of atypical neoplastic, often pleomorphic cells that invade other tissues. "The EGFR has a crucial role in cell differentiation and proliferation and cancer, being ARSB regulation an important target for cancer therapy." (PMID 33445445, 2021). "However, ARSB is known to have its expression reduced in most carcinomas when compared with normal tissues." (PMID 33445445, 2021). "It probably interacts with the Wnt and ARSA/ARSB pathways and is involved in the process of EMT of carcinoma cells." (PMID 31205468, 2019). "Some of the genes were related to animal disease, such as the immunoglobulin binding factor MSMB (β-microseminoprotein), genes encoding the membrane attack complex/perforin protein, as well as cancer related gene headcase and ARSB (arylsulfatase B)." (PMID 27782082, 2016).
genetic disorder (5 papers, 2023 to 2026). "In an autosomal recessive manner, this genetic disorder is inherited, arising from mutations in the ARSB gene on chromosome 5q13-q14." (PMID 39161895, 2024).
metabolic disorder (3 papers, 2018 to 2022). "Mucopolysaccharidosis type VI (MPS VI) is a metabolic disorder caused by disease-associated variants in the Arylsulfatase B (ARSB) gene, resulting in ARSB enzyme deficiency, lysosomal glycosaminoglycan accumulation, and cartilage and bone pathology." (PMID 36561048, 2022). "Mucopolysaccharidosis VI (MPS VI) or Maroteaux-Lamy syndrome is a rare metabolic disorder, resulting from the deficient activity of the lysosomal enzyme arylsulfatase B (ARSB)." (PMID 30524696, 2018).
infection (2 papers, 2017 to 2022). The state of being infected such as from the introduction of a foreign agent such as serum, vaccine, antigenic substance or organism. "The level of hepatic ARSB in schistosomiasis was reported to show changes in activity of the enzyme during the course of the infection." (PMID 36361933, 2022).
neurodegenerative disease (2 papers, 2022 to 2025). A disorder of the central nervous system characterized by gradual and progressive loss of neural tissue and neurologic function. "This study revealed that the five biomarkers, GLB1, ARSB, ASAH1, HEXB, and PSAP are all enriched in the lysosomal, chemokine, oxidative phosphorylation, and neurodegenerative disease pathways." (PMID 40534738, 2025).
adenocarcinoma (1 paper, 2022). A common cancer characterized by the presence of malignant glandular cells. "The ARSB staining intensity and localization differed in malignant colonic tissue from normal colonic epithelium, with distinctive, intense luminal membrane staining reduced in the malignancies and less in the grade 3 than in the grade 1 adenocarcinomas." (PMID 36361933, 2022).
colon (1 paper, 2017). "Investigation of the role of the enzyme ARSB in other malignancies has shown that decline in ARSB is associated with more aggressive prostate and colon malignancies and that ARSB activity is reduced in malignant mammary cells and tissue compared to normal." (PMID 27926479, 2017).
inflammation (1 paper, 2024). Aberrant reaction of the microcirculation characterized by movement of fluid and leukocytes from the blood into extravascular tissues. "In the mouse model of carrageenan-induced systemic inflammation, increases in phospho-p38 MAPK and expression of CHST15 and CHST11 and declines in DNA-E2F binding and ARSB expression occurred in the lung, similar to the observed effects in this SPRBD model of COVID-19 infection." (PMID 38355690, 2024).
prostate (1 paper, 2025). "Declines in both ARSB and in CFTR have been associated with the development of malignancies, including prostate malignancy." (PMID 40362587, 2025).
renal disease (1 paper, 2019). "ARSB is located on chromosome 5q14.1 and has ubiquitous expression in the kidney, but no renal disease has been reported." (PMID 31660881, 2019).
ARSB also shares sentences with these, for which no sentence is quoted: autosomal recessive disease (2 papers); dementia (2); dysostosis multiplex (2); Hearing Loss (2); Mucopolysaccharidosis types I (2); nephrotic syndrome (2); Usher syndrome (2); acute renal failure (1); amyotrophic lateral sclerosis (1); animal disease (1); carotid atherosclerosis (1); colon cancer (1); cutaneous melanoma (1); deafness (1); Huntington disease (1); Lipid storage disease (1); lung disease (1); metastatic melanoma (1); mucopolysaccharidosis II (1); neurodevelopmental disorder (1); osteoporosis (1); prion disease (1); pulmonary fibrosis (1); retinitis pigmentosa (1); scrapie (1); skeletal dysplasia (1); spinal cord injury (1).